Y_RNA (Y RNA )
Gene: Miscellaneous RNA gene on chromosome 4 (59,833,175 to 59,833,276, forward strand). Ensembl gene ENSG00000201676.
Homologues: Orthologues: chimpanzee Y_RNA (100% identical), macaque Y_RNA (80% identical). Paralogues in human: Y_RNA (90% identical), RNY3 (87% identical), Y_RNA (87% identical), RNY3P1 (86% identical), Y_RNA (86% identical), Y_RNA (85% identical), Y_RNA (84% identical), RNY3P14 (83% identical), Y_RNA (83% identical), RNY3P11 (82% identical), Y_RNA (82% identical), RNY3P13 (81% identical), and 93 more.